PROKR2 (prokineticin receptor 2)
Description:
Receptor for prokineticin 2. Exclusively coupled to the G(q) subclass of heteromeric G proteins. Activation leads to mobilization of calcium, stimulation of phosphoinositide turnover and activation of p44/p42 mitogen-activated protein kinase.
Synonyms: GPR73L1; PKR2; GPR73b; GPRg2; dJ680N4.3; HH3; KAL3
Tractability: Small molecule: it belongs to a druggable protein family. Antibody: UniProt places it where antibodies can reach, with high confidence; its Gene Ontology location is reachable by antibodies, with high confidence; UniProt predicts a signal peptide or a membrane-spanning region. PROTAC: a small molecule that binds it is known.
Target class: Peptide growth factor receptor (family A GPCR); Prokineticin receptor; Family A G protein-coupled receptor; Peptide receptor (family A GPCR); Membrane receptor
Gene: Protein-coding gene on chromosome 20 (5,299,218 to 5,316,954, reverse strand). Ensembl gene ENSG00000101292.
Subcellular location: Cell membrane
Pathways (Reactome):
Signal Transduction: G alpha (q) signalling events; Peptide ligand-binding receptors
Gene Ontology:
Molecular function: protein binding; G protein-coupled receptor activity; neuropeptide Y receptor activity
Biological process: cellular response to hormone stimulus; circadian rhythm; G protein-coupled receptor signaling pathway; neuropeptide signaling pathway
Cellular component: plasma membrane; membrane
Genetic constraint (gnomAD): Loss-of-function variants: 26 observed, 24.17 expected, observed/expected ratio (o/e) 1.08, 90% interval 0.79 to 1.49. The upper end of that interval is the gene's LOEUF score, 1.49, which puts it in group 6 of 6, group 1 being the genes least tolerant of losing a copy. Missense variants: 453 observed, 538.13 expected, observed/expected ratio (o/e) 0.84, 90% interval 0.78 to 0.91. Synonymous variants: 212 observed, 211.89 expected, observed/expected ratio (o/e) 1, 90% interval 0.89 to 1.12.
Gene-disease validity (ClinGen):
ClinGen rates the evidence that PROKR2 causes each of these diseases.
hypogonadotropic hypogonadism 3 with or without anosmia (autosomal dominant): Definitive.
Homologues: Orthologues: macaque PROKR2 (99% identical), chimpanzee PROKR2 (98% identical), rabbit PROKR2 (94% identical), dog PROKR2 (94% identical), guinea pig PROKR2 (93% identical), pig PROKR2 (91% identical), rat Prokr2 (90% identical), mouse Prokr2 (90% identical), tropical clawed frog prokr2 (81% identical). Paralogues in human: PROKR1 (87% identical), NPY2R (23% identical), PRLHR (23% identical), NPY5R (22% identical), NPY4R (22% identical), NPY4R2 (22% identical), TACR2 (21% identical), MCHR1 (21% identical), NPY1R (21% identical), TACR1 (21% identical), TACR3 (21% identical), GPR83 (20% identical), and 21 more.
Diseases named in the same sentence as PROKR2 in open-access papers:
PROKR2 is named in the same sentence as 67 diseases in open-access papers, as found by Europe PMC text mining. Sharing a sentence is not in itself a finding about the gene and the disease. The quoted sentences say what the papers report.
Kallmann syndrome (25 papers, 2007 to 2025). Kallmann syndrome (KS) is a developmental genetic disorder characterized by the association of congenital hypogonadotropic hypogonadism (CHH) due to gonadotropin-releasing hormone (GnRH) deficiency, and anosmia or hyposmia (with hypoplasia or aplasia of the olfactory bulbs). "Studies carried out on mouse models showed abundant gene expression in the single-cell RNA of mutated Prokr2 genes in animals affected by Kallmann syndrome." (PMID 38612730, 2024). "Patients carrying mutations in PROKR2 typically present hypogonadotropic hypogonadism, anosmia/hyposmia or Kallmann Syndrome." (PMID 36843573, 2023). "Loss-of-function mutations in prokineticin 2 (PROK2) and the cognate receptor prokineticin receptor 2 (PROKR2) genes have been implicated in reproductive deficits characteristic of Kallmann Syndrome (KS)." (PMID 36686573, 2022). "We have identified a gene regulatory network, Gsx1/2 – Dlx1/2/5/6 – GAD2/1/Sp8/Sp9 – Tshz1 – Prokr2, which governs OBiN development; mutations of some of these genes result in human Kallmann syndrome with abnormal olfactory function (anosmia or hyposmia)." (PMID 34374948, 2022). "The p.Leu173Arg PROKR2 variant, in both heterozygous or homozygous status, has been reported several times in individuals with Kallman syndrome or hypogonadotropic hypogonadism, showing very variable phenotypes." (PMID 33401665, 2021). "This study involved two unrelated Tunisian patients with HH, which was triggered by identifying a homozygous p.(Pro290Ser) mutation in the PROKR2 gene in a girl (HH1) with Kallmann syndrome (KS)." (PMID 34539727, 2021). "In humans, patients with mutations in PROKR2 can present with hypogonadotropic hypogonadism or Kallmann syndrome." (PMID 33634051, 2020). "The PROKR2 p.R85C variant has been described in a heterozygous state in patients with idiopathic hypogonadotropic hypogonadism, Kallmann syndrome, healthy first-degree relatives of Kallmann probands, and rare healthy controls." (PMID 28453858, 2017). "Other recent studies found malformation of the olfactory bulb and gonadotropin-releasing hormone deficiency in PROK2/PROKR2-knockout mice and patients with Kallmann syndrome or hypogonadotropic hypogonadism harboring the PROK2/PROKR2 mutation." (PMID 26317645, 2015). "Four of those variants, detected in PROKR2, had been previously reported as mutations associated to Kallmann Syndrome." (PMID 21858136, 2011). "The phenotypes of Prokr2 and Prok2 knockout mice model aspects of human Kallman syndrome (KS), a partially penetrant genetic disease that causes OB deformity and consequently anosomia and hypogonadism with associated sterility and failure to reach puberty." (PMID 18052978, 2007). "Furthermore, PROKR2 mutations are associated with Kallmann syndrome, a rare disease characterized by delayed puberty, impaired sense of smell, and kidney abnormalities, indicating a possible link to kidney development disorders." (PMID 40770708, 2025). "In addition, in the mouse model of PROKR2 deficiency, the Kallmann syndrome phenotype is observed only in the homozygous animals." (PMID 28453858, 2017). "Moreover, mutations in PROKR2 lead to GnRH-deficiency and more specifically to Kallmann syndrome, a disease characterized by hypogonadism, a decreased functional activity of the gonads." (PMID 27673331, 2016). "Interestingly, mutations in PROKR2 linked to Kallmann syndrome have been shown to impair Ca2+ release in HEK293 cells, which is consistent with the effect of oxandrolone on PKR2 in the same cell lines detected herein." (PMID 27673331, 2016). "Furthermore, inactivating mutations of PROK2 and PROKR2 have been discovered in 2–7% of patients with Kallmann syndrome, who suffer from anosmia and hypogonadotropic hypogonadism." (PMID 26313571, 2015).
Kallmann syndrome (continued). "The occurrence of disease-associated monoallelic mutations may not be rare; for example, this appears to be a common mechanism in Kallmann syndrome caused by mutations in PROKR2 or PROK2 (i.e., an autosomal recessive mode of disease transmission)." (PMID 25077171, 2014). "As has been described in mice, impairment of PROKR2-mediated migration of neurons, particularly interneurons, to the olfactory bulb is sufficient to explain the anosmia or hyposmia phenotype." (PMID 36843573, 2023). "Kallmann syndrome caused by ANOS1 gene mutations is inherited by X-linked recessive trait as it is located on chromosome X. FGFR1 and PROK2/PROKR2 lead to autosomal dominantly inherited type of CHH." (PMID 32222824, 2021). "In Kallmann syndrome, anosmia/hyposmia is part of the clinical picture, and ANOS1, CHD7, FGFR1, PROK2, PROKR2, and SEMA3A variants were reported to be involved in isolated congenital anosmia." (PMID 32222824, 2021). "According to these authors’ assessment, mutations in KAL1 appear in about 8% of cases of Kallmann syndrome, FGF8 and FGFR1 both appear in about 10% of cases and mutations both in PROKR2 or PROK2 are responsible for about 9% of cases." (PMID 32722328, 2020). "Genetic mutations implicated in Kallmann syndrome (KS), such as KAL1, FGFR1, PROKR2, and FGF8, have also been recently identified in patients with SOD." (PMID 33634051, 2020). "Mutations in PROKR2 have previously been associated with hypogonadotropic hypogonadism with or without anosmia and Kallmann syndrome." (PMID 28453858, 2017). "We therefore propose that p.R85C (and possibly other PROKR2 mutations) may act as a modifier and contribute to the PSIS phenotype through digenic inheritance, as previously demonstrated in idiopathic hypogonadotropic hypogonadism and Kallmann syndrome." (PMID 28453858, 2017). "However, no clinical signs or symptoms of Kallmann syndrome were observed in HSCR patients carrying PROKR2 variants." (PMID 21858136, 2011). "As far as is known, this is the first report evidencing digenic mutations in patients with KS and P/LP variants in PROKR2 and GLI2 (PROKR2: p.R85H and GLI2: p.A185S) genes (proband 30 with anosmia, absence of puberty, and micropenis)." (PMID 34198905, 2021).
hypogonadotropic hypogonadism (12 papers, 2011 to 2025). Abnormal ovarian or testicular function due to insufficient hormonal stimulation from the hypothalamic-pituitary axis. "Prokineticin receptor 2 (PROKR2) loss of function mutations have been described as cause of hypogonadotropic hypogonadism." (PMID 33413516, 2021). "Utilizing multiplex PCR for the four gene KS/IHH panel followed by NGS, we describe herewith two cases of hypogonadotropic hypogonadism with a Prokineticin receptor 2 (PROKR2) gene and KAL1 gene mutation." (PMID 31781422, 2019). "Congenital central hypogonadism is believed to be caused by genetic pathogenic variants, with genes such as ANOS1, FGFR1, FGF8, PROKR2, and PROK2 being implicated." (PMID 39817151, 2025). "Additionally, genetic causes of isolated hypogonadotropic hypogonadism such as KAL1, FGFR1/FGF8, PROKR2/PROK2, CHD7, or GNRH1 gene mutations have not been studied because the patient had a normal puberty and regular menstruation before the amenorrhea." (PMID 26266058, 2015).
hypogonadism (6 papers, 2007 to 2023). A disorder characterized by decreased function of the gonads. "PROKR2 is traditionally known as a gene implicated in hypogonadism hypogonadotropic, involved in pituitary ontogenesis." (PMID 37605180, 2023). "The inactivation of PROK2 or PROKR2 lead to defective olfactory morphogenesis and hypogonadism in mice and humans." (PMID 23596439, 2013). "In these patients, hypogonadism is due to a failure of embryonic migration of gonadotropin-releasing hormone-synthesizing neurons from the olfactory epithelium to the forebrain, and insufficient prokineticin signalling through PROKR2 seems to play a critical role." (PMID 21858136, 2011).
congenital hypogonadotropic hypogonadism (4 papers, 2013 to 2024). Congenital hypogonadotropic hypogonadism (CHH) is a rare disorder of sexual maturation characterized by gonadotropin (Gn) deficiency with low sex steroid levels associated with low levels of follicle stimulating hormone (FSH) and luteinizing hormone (LH). "Importantly, allelic variants of PROKR2 in humans are associated with altered migration of GnRH neurons, resulting in congenital hypogonadotropic hypogonadism (CHH), a heterogeneous disease characterized by delayed/absent puberty and/or infertility." (PMID 32376893, 2020). "Interestingly, few patients who had monoallelic missense mutations both in PROK2 or PROKR2, and in other KS or normosmic congenital hypogonadotropic hypogonadism genes, raising the idea of oligogenism." (PMID 23596439, 2013). "Other variants were identified in genes know to be associated with congenital hypogonadotropic hypogonadism (CHH), including the CHD7 and PROKR2 genes." (PMID 36110220, 2022). "Genes which are associated with congenital hypogonadotropic hypogonadism include : the Fibroblast Growth Factor receptor 1 gene (FGFR), prokineticin receptor 2 gene (PROKR2), GNRH receptor gene (GNRHR) and the Kallmann syndrome 1(KAL1) sequence gene (also known as ANOS-1)." (PMID 38062345, 2024).
cryptorchidism (4 papers, 2017 to 2024). The failure of one or both testes of a male fetus to descend from the abdomen into the scrotum during the late part of pregnancy. "In contrast, the patient DSD-0016 with a monoallelic PROKR2 variant presented with more severe phenotypes, including bilateral cryptorchidism, growth retardation, and facial dysmorphia." (PMID 39285472, 2024). "From this, we hypothesise that PROKR2 variants, in particular the variant p.S188L, represent a significant cause of under-virilisation including cryptorchidism, micropenis and, in some cases, hypospadias in Indonesian 46,XY DSD patients." (PMID 28209183, 2017).
Infertility (4 papers, 2009 to 2022). "Knock out of Prokr2 gene produces the KS-like phenotype in mice resulting in impaired migration of gonadotropin releasing hormone (GnRH) neurons, olfactory bulb dysgenesis, and infertility." (PMID 36686573, 2022). "Recently, specific phenotypes of PROKR2 and PROK2 knockout mice, have been identified as causative genes for idiopathic hypogonadotropic hypogonadism, a developmental disorder characterized by impaired development of gonadotropin-releasing hormone neurons and infertility." (PMID 33194559, 2020). "The complete infertility in genetically modified mice lacking kisspeptin and its cognate receptor GPR54, or lacking prokineticin 2 or prokineticin receptor 2 suggests that some peptidergic systems are of critical importance in hypothalamic control of fertility." (PMID 19390688, 2009).
Arthritis (3 papers, 2010 to 2022). Inflammation of a joint. "A lack of MMP-8 causes the aggravation of arthritis through promotion of inflammation by IL-1β and PTX3, inducing the maturation and activation of osteoclasts or enhancement of the inflammatory infiltrate by PROKR2 and IL-1β." (PMID 28445942, 2017).
CHARGE syndrome (3 papers, 2013 to 2025). CHARGE syndrome is a multiple congenital anomaly syndrome characterized by the variable combination of multiple anomalies, mainly Coloboma; Choanal atresia/stenosis; Cranial nerve dysfunction; Characteristic ear anomalies (known as the major 4 C's). "These include the genes KAL1, FGFR1, FGF8 which encodes the ligand of FGFR1, PROKR2 and PROK2, NELF (nasal embryonic factor) and mutations in CHD7 associated with the CHARGE syndrome." (PMID 24204987, 2013). "Although CHD7 was originally considered to be the causative gene for CHARGE syndrome, subsequent research showed that CHD7 mutations can also be detected in KS patients lacking mutations in KAL1, FGFR1, PROK2, and PROKR2." (PMID 34231173, 2022).
neuroblastoma (3 papers, 2011 to 2024). Neuroblastoma (NB) is the most common solid, extracranial childhood tumor. "PROKR2 transcripts are significantly high expressed to activate prokineticin signaling and inhibit apoptosis in the advanced stages of neuroblastoma, which contributes to human neuroblastoma progression." (PMID 32887509, 2020). "PROKR2 is essential for inhibiting neuroblastoma cell apoptosis." (PMID 38164347, 2024).
Obesity (3 papers, 2019 to 2025). Accumulation of substantial excess body fat. "Further connecting both conditions, we observed up‐regulation in Cpne5 expression, previously associated with both AD and obesity, and Prokr2, a gene involved in circadian rhythms." (PMID 40944384, 2025). "Some patients exhibited olfactory dysosmia and obesity, which was consistent with the clinical manifestations of extreme obesity in patients with PROKR2 variants reported in previous studies." (PMID 35090434, 2022). "Monogenic forms, such as hemizygous ANOS1 mutations or biallelic GnRHR or PROKR2 variants, can explain the more severe phenotypes whereas various combinations of minor IHH alleles with or without acquired factors, such as obesity, can justify the adult-onset of IHH." (PMID 30669598, 2019).
pituitary stalk interruption syndrome (3 papers, 2017 to 2023). "Until now, 37 cases harboring PROKR2 mutations presented pituitary diseases: the majority were CPHD and IGHD, followed by septo-optic dysplasia and pituitary stalk interruption syndrome." (PMID 36843573, 2023).
adenoma (2 papers, 2021 to 2023). A neoplasm arising from the epithelium. "Furthermore, analysis of genetic sequencing has identified genetic variations (e.g., in LINC01605, PROKR2, and CCSER1 genes) linked to constituents of the metabolome or microbiome, as well as the risk of adenoma or colorectal cancer." (PMID 37012201, 2023).
central precocious puberty (2 papers, 2021 to 2023). "In 2017, a first case of central precocious puberty (CPP) caused by PROKR2 heterozygous gain of function mutation was described in a 3.5 years-old girl." (PMID 33413516, 2021). "However, another study including 31 female patients with central precocious puberty aimed to further strengthen the link between PROKR2 and CPP and no genotype-phenotype correlations were found." (PMID 36843573, 2023).
Hirschsprung disease (2 papers, 2017 to 2019). Hirschsprung disease (HSCR) is a congenital intestinal motility disorder that is characterized by signs of intestinal obstruction due to the presence of an aganglionic segment of variable extent in the terminal part of the colon. "Genetic mutations in PROKR1 are associated with Hirschsprung's disease [1688], while genetic mutations in PROKR2 are associated with hypogonadotropic hypogonadism with anosmia, hypopituitarism with pituitary stalk interruption [1649] and Hirschsprung's disease [1688]." (PMID 29055040, 2017).
hypopituitarism (2 papers, 2017 to 2023). A condition of diminution or cessation of secretion of one or more hormones from the anterior pituitary gland. "In recent years, reports associating PROKR2 variants to hypopituitarism and related disorders have emerged." (PMID 36843573, 2023). "For example, heterozygous mutations, including PROKR2 c.254G>A;p.R85H (rs74315418), c.253C>G;p.R85G (rs141090506), and c.254G>T;p.R85L (rs74315418), have all been identified in association with pituitary stalk interruption and combined pituitary hormone deficiencies." (PMID 28453858, 2017).
hypospadias (2 papers, 2017 to 2022). Hypospadias is the displacement of the urethral meatus on the ventrum of the penis. "We conclude that variants in CHH genes, in particular PROKR2, PROK2, WDR11 and FGFR1 with CHD7, may contribute to under-virilisation phenotypes including hypospadias in Indonesian boys." (PMID 28209183, 2017). "We postulate that variants in CHH genes, in particular PROKR2, PROK2, WDR11 and FGFR1 with CHD7, may contribute to under-virilisation phenotypes including hypospadias in Indonesia." (PMID 28209183, 2017).
major depressive disorder (2 papers, 2011 to 2025). An episode of depression lasting two or more weeks without an intervening episode of mania. "On the other hand, we detected the associations between PROKR2 and not only mood disorders including major depressive disorder and bipolar disorder but also METH dependence and METH-induced psychosis in the Japanese population." (PMID 21886577, 2011).
methamphetamine dependence (2 papers, 2011 to 2022). A drug dependence that is a psychological dependency on the regular use of methamphetamine. "A study reported that the prokineticin 2 receptor gene (PROKR2), which has been shown to be essential for circadian rhythm, is a common susceptibility gene for methamphetamine dependence and mood disorders." (PMID 35439968, 2022). "Recently, we detected the significant association between prokineticin 2 receptor gene (PROKR2) and Japanese methamphetamine dependence patients." (PMID 21886578, 2011).